BACH1 (BACH transcriptional regulator 1)
Description:
Transcriptional regulator that acts as a repressor or activator, depending on the context. Binds to NF-E2 DNA binding sites. Plays important roles in coordinating transcription activation and repression by MAFK (By similarity). Together with MAF, represses the transcription of genes under the control of the NFE2L2 oxidative stress pathway.
Synonyms: BACH-1; BTBD24; C21orf41; NCRNA00258; GRIK1-AS2
Tractability: Small molecule: it has a binding pocket of medium quality. PROTAC: UniProt records ubiquitination sites on it; ubiquitination databases record sites on it; its protein half-life has been measured; a small molecule that binds it is known.
Target class: Transcription factor
Safety:
Unwanted effects reported when the protein is acted on. In parentheses: how it was acted on, where the effect was seen, and who reports it.
liver injury (source: ClinPGx)
Gene: Protein-coding gene on chromosome 21 (29,194,071 to 29,630,751, forward strand). Ensembl gene ENSG00000156273.
Subcellular location: Nucleus
Subcellular location (Human Protein Atlas): Nucleoplasm; Cytosol
Pathways (Reactome):
Cellular responses to stimuli: Heme signaling; NFE2L2 regulating anti-oxidant/detoxification enzymes; Regulation of BACH1 activity; Regulation of HMOX1 expression and activity
Gene Ontology:
Molecular function: DNA-binding transcription repressor activity, RNA polymerase II-specific; ligand-modulated transcription factor activity; protein binding; DNA-binding transcription factor activity; DNA-binding transcription factor activity, RNA polymerase II-specific; heme binding; RNA polymerase II cis-regulatory region sequence-specific DNA binding; DNA binding; DNA-binding transcription activator activity, RNA polymerase II-specific
Biological process: DNA repair; negative regulation of transcription by RNA polymerase II; regulation of DNA-templated transcription; regulation of transcription by RNA polymerase II; positive regulation of transcription by RNA polymerase II
Cellular component: cytoplasm; cytosol; nucleus; RNA polymerase II transcription regulator complex; chromatin; nucleoplasm
Genetic constraint (gnomAD): Loss-of-function variants: 33 observed, 52.78 expected, observed/expected ratio (o/e) 0.63, 90% interval 0.47 to 0.84. The upper end of that interval is the gene's LOEUF score, 0.84, which puts it in group 3 of 6, group 1 being the genes least tolerant of losing a copy. Missense variants: 807 observed, 909.97 expected, observed/expected ratio (o/e) 0.89, 90% interval 0.84 to 0.94. Synonymous variants: 321 observed, 331.39 expected, observed/expected ratio (o/e) 0.97, 90% interval 0.88 to 1.06.
Homologues: Orthologues: chimpanzee BACH1 (99% identical), macaque BACH1 (98% identical), dog BACH1 (88% identical), pig BACH1 (86% identical), guinea pig BACH1 (83% identical), rabbit BACH1 (82% identical), mouse Bach1 (81% identical), rat Bach1 (80% identical), tropical clawed frog bach1 (49% identical), zebrafish bach1b (29% identical), zebrafish bach1a (27% identical). Paralogues in human: BACH2 (36% identical), KLHL22 (13% identical), KLHL5 (13% identical), KLHL36 (12% identical), KLHL26 (12% identical), KLHL3 (12% identical), KLHL4 (12% identical), KLHL1 (12% identical), KLHL14 (12% identical), KLHL2 (12% identical), KLHL21 (12% identical), KLHL32 (12% identical), and 42 more.
Diseases named in the same sentence as BACH1 in open-access papers:
BACH1 is named in the same sentence as 167 diseases in open-access papers, as found by Europe PMC text mining. Sharing a sentence is not in itself a finding about the gene and the disease. The quoted sentences say what the papers report.
lung cancer (73 papers, 2016 to 2025). A malignant neoplasm involving the lung. "Experimental studies in lung cancer mouse models demonstrate that KEAP1 or FBXO22 deficiency promotes metastatic spread through BACH1-mediated mechanisms." (PMID 40507333, 2025). "To address this, we performed RNA-Seq coupled with ChIP-Seq in BACH1-proficient and BACH1-deficient lung cancer cells, identifying a set of direct BACH1 target genes." (PMID 40716152, 2025). "BACH1 facilitates the progression and metastasis of lung cancer and is additionally implicated in various other respiratory diseases." (PMID 39887888, 2025). "In lung cancer, BACH1 overexpression is linked to poor prognosis and metastasis, yet a consistent transcriptional signature reflecting its activity has not yet been defined." (PMID 40716152, 2025). "Further STRING database and RNA-seq analyses also support the positive association between BACH1 and glycolytic gene expression in lung cancer." (PMID 38321558, 2024). "Previous research has linked BACH1 to enhanced metastatic potential across a variety of cancers, including breast and lung cancers." (PMID 38838145, 2024). "As Nrf-2 induces HO-1, the enzyme catabolizing heme, its accumulation in lung cancer tissue causes the stabilization of transcription regulator protein BACH1 (BACH1), a pro-metastatic transcription factor whose degradation is triggered by heme." (PMID 36701089, 2023). "Given that tumors characterized by high BACH1 levels often arise in patients with NRF2/KEAP1 mutations, targeting BACH1 or its upstream/downstream proteins represents a promising strategy to combat lung cancer metastasis." (PMID 38202657, 2023). "BACH1 is well established as a promoter of cancer metastasis, especially in non‐small cell lung cancers with NFE2L2 mutation." (PMID 36453019, 2023). "Nrf2 accumulation in lung cancers causes the stabilization of Bach1 by inducing HO-1, the enzyme catabolizing heme." (PMID 36014573, 2022). "Obviously, BACH1 serves as a diagnostic marker to stratify patient outcomes with numerous cancer types including breast and lung cancer." (PMID 33809182, 2021). "Higher Bach1 levels indicate a higher risk of human cancers, such as colorectal cancer, glioblastoma, and lung cancer." (PMID 34949193, 2021). "Another regulatory mechanism of BACH1 expression includes mutation in either Keap1 or Nfe2l2 that comprises about 30% of human lung cancer." (PMID 33809182, 2021). "Bach1 is considered as a key factor in responding to conditions of oxidative stress and is associated with poor survival and metastasis in lung cancer patients." (PMID 33596919, 2021). "Either antioxidant treatment-induced BACH1 or Keap1 loss-induced Bach1 promoted lung cancer metastasis." (PMID 33809182, 2021). "Consistently, a transcriptional signature that includes Bach1 and its target genes showed strong association with poor survival, advanced clinical stage and grade, and metastasis in lung cancer patients." (PMID 33809182, 2021). "The accumulation of NRF2 in lung cancer promotes the stabilization of BACH1, and the loss of KEAP1 or FBXO22 induces metastasis in a BACH1-dependent manner." (PMID 32429232, 2020). "Lignito’s results showed that loss of Keap1 or Fbxo22 induces metastasis in a Bach1-dependent manner and causes a notable increase in the metastatic phenotype in mouse models of lung cancers." (PMID 32629428, 2020). "Recently, higher levels of BACH1 were found to be associated with poor prognosis in human ovarian cancer and to promote lung cancer metastasis." (PMID 32132179, 2020). "Importantly, high levels of functional BACH1 have been associated with aggressive cancer phenotypes and poor patient prognosis in lung cancer." (PMID 40665337, 2025).
lung cancer (continued). "Moreover, BACH1 transcriptional signature is associated with poor survival and metastasis in lung cancer patients." (PMID 36701089, 2023). "Stabilization of Bach1 was recently implicated in lung cancer metastasis." (PMID 34807950, 2021). "One example is that exogenous antioxidant treatment such as N-acetyl cysteine (NAC) or vitamin E in a water-soluble could promote metastasis process of KRas-mutated lung cancer cells, through reducing intracellular free heme that increases BACH1 proteins levels." (PMID 33809182, 2021). "Recent studies indicate that PDLIM2 repression in the lung macrophages of mice with lung cancer is attributed to the transcription repressor BACH1 activated by reactive oxygen species (ROS)." (PMID 41346604, 2025). "While it appears that the pro-metastatic role of BACH1 is tumour-type agnostic, the most robust data comes from studies in lung cancer." (PMID 40716152, 2025). "In this manuscript, we discuss the identification of a novel, specific and sensitive BACH1 lung cancer signature, which is also relevant in other tissue types." (PMID 40716152, 2025). "Increased BACH1 expression has been observed in various malignancies, including lung cancer, where it modulates processes such as oxidative stress response, cell cycle regulation, mitosis, and cellular senescence." (PMID 40665337, 2025). "This novel lung cancer BACH1 signature is highly sensitive and specific to BACH1 perturbation, unaffected by NRF2 modulation, and consistent across a large panel of cancer cell lines." (PMID 40716152, 2025). "For instance, the activation of Nrf2 potentiates lung cancer metastasis by inhibiting the heme- and Fbxo22-mediated degradation of Bach1." (PMID 40563308, 2025). "In this manuscript, we report the identification of a novel BACH1 lung cancer signature that is also conserved in other cell types." (PMID 40716152, 2025). "BACH1 expression in tumor sections of lung cancer patients is relevant to the expression of angiogenic genes and proteins." (PMID 39887888, 2025). "Using our signature, we identified HTRA3 as a potential novel effector of BACH1's pro-migratory effect in human lung cancer cells." (PMID 40716152, 2025). "Analogously, NRF2 knockdown reduced angiogenesis, concordant with tumor growth reduction, in xenograft models, while NRF2 activation in lung cancer stabilized BACH1 by inducing heme oxygenase 1 (HO1)." (PMID 40507333, 2025). "BACH1 stability is sensitive to heme or hemin, which are essential for E3 ubiquitin ligases, including HOIL-1 and FBXO22, mediated BACH1 degradation via proteasome in lung cancer cells." (PMID 40263598, 2025). "In previous studies, NRF2 activation stabilized BACH1 protein via inducing HO-1 for heme degradation, leading to high levels of metastasis in lung cancers." (PMID 40263598, 2025). "The signature works in most cells (but not in all), demonstrating that induction of HMOX1, ZNF469 and HTRA3 is a strong surrogate for BACH1 depletion in lung cancer cells and a good pan-tissue BACH1 signature." (PMID 40716152, 2025). "Approximately 30% of human lung cancers gain mutations affecting Keap1 or NFE2L2 (encoding Nrf2), which lead to the stabilization of Nrf2, influence the nuclear transport of BACH1/Nrf2, and upregulate the expression of HO-1, thereby combating oxidative stress." (PMID 38321558, 2024). "Antioxidants stabilize BACH1 to promote lung cancer metastasis, which depends on glycolysis and lactate secretion and is related to high ATP production rates." (PMID 38321558, 2024). "In lung cancer, BACH1 promotes the expression of CD44+, thereby inducing the proliferation and invasion of lung CSCs both in vivo and in vitro." (PMID 38321558, 2024). "BACH1 has been identified as an important pro-metastatic factor in various cancer types, including lung cancer, colorectal cancer, and breast cancer." (PMID 38838145, 2024). "The reduced concentration of free heme subsequently stabilizes BACH1, which in turn promotes lung cancer metastasis." (PMID 38895309, 2024).
lung cancer (continued). "Combined treatment with these drugs decreases glycolysis rates and effectively reverses the BACH1-induced migration of lung cancer cells." (PMID 38321558, 2024). "Another study using a lung cancer metastasis model showed that NRF2 activation leads to the stabilization of BACH1 and HO-1, both playing pivotal roles in promoting metastasis." (PMID 38247494, 2024). "In lung cancer, the upregulation of BACH1 is mediated by the inhibition of free heme via heme oxygenase-1 (HO-1)." (PMID 37239002, 2023). "Analyses of The Cancer Genome Atlas (TCGA) data revealed that BACH1 expression in lung cancers correlates with the expression of a broad range of angiogenesis and glycolysis genes; we observed similar results in breast and kidney cancer cohorts." (PMID 37651203, 2023). "Our data demonstrate that BACH1 in lung cancer cells was activated during hypoxia and in response to antioxidant administration through both transcriptional and posttranslational mechanisms." (PMID 37651203, 2023). "This recent important work suggests that oxidative stress suppressed by antioxidants can in turn increase the stability of BACH1 and promote its accumulation in lung cancer cells." (PMID 37597078, 2023). "Antioxidants thus stimulate aerobic glycolysis and increase local and distant lung cancer metastasis in a BACH1-dependent fashion." (PMID 37651203, 2023). "BACH1 expression in tumor sections from patients with lung cancer correlated with angiogenesis gene and protein expression." (PMID 37651203, 2023). "On the other hand, BACH1 can promote metastasis in breast cancer, ovarian cancer, lung cancer and pancreatic cancer." (PMID 37963558, 2023). "In lung cancer, the BACH1 protein can promote glycolytic metabolism, intracellular glucose uptake, and lactate excretion." (PMID 37946265, 2023). "Our study demonstrates that both CDDO-TFEA and CDDO-Me are very potent dual KEAP1 and BACH1 inhibitors, and that they reduce lung cancer cell invasion in a BACH1-dependent and NRF2-independent manner." (PMID 35313207, 2022). "BACH1 promotes lung cancer cell migration and invasion by inducing the expression of metabolic genes (such as HK2) leading to an increase in glycolysis, and thus BACH1 inhibitors have the potential to reduce the spread of lung cancer cells." (PMID 35313207, 2022). "It is reported that loss of Nrf2 in an oncogenic context-dependent manner can enhance cellular plasticity and motility, in part by using TGF-β/Smad signaling, and Nrf2 activation promotes lung cancer metastasis by inhibiting the degradation of Bach1." (PMID 36014573, 2022). "Previously, hemin, also known as exogenous free heme, effectively induces the degradation of BACH1 protein in breast tumors in vivo, as well as breast and lung cancer cells, to subsequently modify cancer metabolism in a BACH1-dependent manner." (PMID 35406740, 2022). "Keap1 loss and Nrf2 activation promotes lung cancer metastasis by accumulating BTB domain and CNC homolog 1 (Bach1), which has been reported to stimulate transcription of HK2 triggering glycolysis-induced metastasis." (PMID 36419136, 2022). "In an in vitro model, both CDDO-derivatives impaired lung cancer cell invasion in a BACH1-dependent and NRF2-independent manner, while CDDO was inactive." (PMID 35313207, 2022). "Further, we found that PDLIM2 was decreased in lung macrophages by oxidative stress–activated transcription repressor BTB and CNC homology 1 (BACH1), and that PDLIM2 repression was associated with poor survival of patients with lung cancer." (PMID 33539325, 2021). "A previous study demonstrated that Nrf2 leads to Bach1 accumulation in lung cancer and promotes lung cancer metastasis in a Bach1-dependent manner." (PMID 34772403, 2021). "Previously, we reported that chronic intermittent hypoxia induced lung cancer stem cell-like properties through enhancing Bach1 expression." (PMID 34949193, 2021).
lung cancer (continued). "Inhibition of glycolysis pathways, therefore, was effective to suppress cancer metastasis in both antioxidant-treated and Bach1-induced lung cancer models." (PMID 33809182, 2021). "Consistent with the in vitro data, BACH1 was mainly in the nucleus of AMs in mice with lung cancer but in the cytoplasm in untreated mice." (PMID 33539325, 2021). "Aerobic glycolysis in the presence of oxygen represents convergent cancer metabolic phenotypes, providing a diagnostic foundation for tumor detection, and this aerobic glycolysis is regulated by BACH1 in lung cancer cells." (PMID 33809182, 2021). "Consistent with findings in breast and lung cancer, BACH1 expression has been shown to be inversely correlated with OXPHOS pathway in TCGA datasets from breast, pancreas, ovary, skin, lung, liver, colon and prostate cancer." (PMID 33499022, 2021). "The elevated HO-1 inhibits the heme-and Fbxo22 (a heme-regulated ubiquitin ligase)-mediated degradation of BACH1 and further promotes lung cancer metastasis." (PMID 34439295, 2021). "Our data also identified PDLIM2 downregulation in AMs and monocytes by ROS-activated BACH1 to increase STAT3 activation as a mechanism driving these immune cells to promote lung cancer." (PMID 33539325, 2021). "In summary, we imply that Bach1 demonstrates great potential for the treatment of lung cancer metastasis and recurrence via activating CD44 and MPAK signaling." (PMID 34949193, 2021). "Pharmacological inhibition of HMOX1 using ZnPPIX was able to suppress lung cancer metastasis by inducing Bach1-destabilization in a Fbxo22-dependent manner." (PMID 33809182, 2021). "In this study, we found that the expression level of Bach1 was increased in lung cancer nodules from CIH-treated mice and NSCLC cells exposed to CIH conditions accompanied by an increased mtROS." (PMID 33596919, 2021). "This study has some limitations: there lacks clinical evidence that lung cancer tissues from NSCLC patients with OSA present a higher Bach1 expression and lung CSC properties than those from NSCLC patients without OSA." (PMID 33596919, 2021). "BACH1 stimulates glycolysis-dependent metastasis of mouse and human lung cancer cells by activating transcription of Hexokinase 2 and Gapdh and increasing glucose uptake, glycolysis rates, and lactate secretion." (PMID 33920079, 2021). "Experiments using mouse xenograft models of human cancer cells, with genetic manipulations of BACH1, have established that BACH1 promotes metastasis of breast cancer, non–small cell lung cancer, pancreatic ductal adenocarcinoma (PDAC), and ovarian cancer." (PMID 34339740, 2021). "Transcription factor BACH1 stimulates glycolysis-dependent lung cancer metastasis by increasing glucose uptake, glycolysis rates, and lactate secretion." (PMID 33403045, 2021). "Similar to in lung cancer, BACH1 silencing in breast cancer cells promotes mitochondrial respiration and TCA cycle and concomitantly reduces glycolytic rate and lactate production." (PMID 33499022, 2021). "In lung cancer, administration of antioxidants N-acetylcysteine or vitamin E reduces level of free heme, which stabilizes Bach1." (PMID 34807950, 2021). "Bach1 was obviously increased in lung cancer nodules from Tumor + CIH mice compared with those from Tumor + Nor mice." (PMID 33596919, 2021). "In a tumor, BACH1 promotes invasion and metastasis of cancer cells, and the expression of BACH1 presents a poor outcome for cancer patients including breast and lung cancer patients." (PMID 33809182, 2021). "The more deteriorated lung cancer associated with CIH can be partly explained by mtROS accumulation and increased Bach1 expression, resulting in enhanced CSC-like property." (PMID 33596919, 2021). "BACH1 works as a metabolic driver in response to the intracellular and extracellular signals in breast and lung cancer cells." (PMID 33809182, 2021).